APP (amyloid beta precursor protein)
Diseases named in the same sentence as APP in open-access papers (continued):
Sharing a sentence is not in itself a finding about the gene and the disease.
Anxiety (continued). "Correspondingly, the unaltered locomotor activity with a moderate increase in time spent in the open field center points to a maintained exploratory drive or reduced level of anxiety with age in APP/PS1/Hif-p4h-2gt/gt mice." (PMID 40609789, 2025). "The Morris water maze (MWM) and open field tests (OFT) were employed to assess the cognitive function and anxiety-related behavior of APP/PS1 mice." (PMID 40066331, 2025). "Behavioral analysis revealed that untreated APP/PS1 mice exhibited disrupted associative learning, increased anxiety-like behavior, as evidenced by reduced exploration in the dark–light box and novelty-suppressed exploration in the novel cage paradigm." (PMID 40801602, 2025). "In the present study, APP/IR‐dKI mice also exhibited enhanced depression and anxiety compared with APP‐KI mice." (PMID 40443027, 2025). "The effect of Ginsenoside Ro on spatial exploration ability and anxiety state in APP/PS1 mice was assessed using the open field test." (PMID 40066331, 2025). "The APP/PS1/tau mice treated with rolipram for 10 days show a significant attenuation of anxiety‐ and depression‐like behaviors by increasing cAMP/PKA signaling and decreasing neuroinflammation." (PMID 39868480, 2025). "In this study’s behavioral experiments, we first used the open field test to assess how Danggui Shaoyao San and its disassembled prescriptions affect anxiety in APP/PS1 mice." (PMID 40822397, 2025). "We first performed elevated cross maze and forced swimming tests in mice to show that TSA indeed ameliorated anxiety- and depression-like behavior in APP/PS1 mice." (PMID 38572429, 2024). "As for other neuronal changes, a decline in hippocampal CA2 activity correlates with anxiety-related behavior in female APP/PS1 mice." (PMID 39703925, 2024). "Homozygous APP-NLGF mice that exhibit anxiety-like behaviors have widespread Aβ deposition at 6 months of age." (PMID 39703925, 2024). "One genotype effect was observed, where female sham-irradiated APP;E4F mice had significantly less anxiety-like behavior than female sham-irradiated APP;E3F mice (p = 0.0411)." (PMID 39273325, 2024). "We found that pharmacological activation of SIRT1 also alleviates anxiety- and depression-like behaviors in APP/PS1 mice." (PMID 39744519, 2024). "The present study will examine the effects of 8 weeks of treadmill exercise on anxiety- and depression-like behaviors in six-month-old APP/PS1 mice." (PMID 39744519, 2024). "Here, we extended our previous study and further demonstrated that treadmill exercise improved anxiety- and depression-like behaviors in APP/PS1 mice." (PMID 39744519, 2024). "Together, these data suggest that six-month-old APP/PS1 mice exhibited anxiety-like behavior, and treadmill exercise alleviated this behavior in the APP/PS1 mice." (PMID 39744519, 2024). "The results of this study indicated that TSA administration relieved the behaviors of depression and anxiety in APP/PS1 mice, and decreased CST7 levels in the hippocampus of APP/PS1 mice and LPS-induced BV2 cells." (PMID 38572429, 2024). "Pharmacological activation of hippocampal SIRT1 function also reduced anxiety and depression-like behaviors in APP/PS1 mice." (PMID 39744519, 2024). "We investigate the behavioral effects of SRT2104, a selective SIRT1 activator, and Resveratrol, one of the most potent natural SIRT1 activator, on anxiety- and depression-like behaviors in APP/PS1 mice." (PMID 39744519, 2024). "Here, we set out to investigate the effects of TSA on anxiety- and depression-like behavior in APP/PS1 transgenic AD mouse model." (PMID 38572429, 2024). "In aged APP/PS1 mice with anxiety-like phenotypes, there are decreases in hippocampal volume and neuronal number." (PMID 39703925, 2024). "In the elevated plus maze test, the APP mice spent significantly more time traveling in the open arms than WT mice, indicating that APP mice have lower anxiety-related behavior." (PMID 39443966, 2024).
Anxiety (continued). "Here, we demonstrate that treadmill exercise improved anxiety- and depression-like behaviors in 6-month-old APP/PS1 mice, while also increasing hippocampal SIRT1 levels." (PMID 39744519, 2024). "And these PTZ-induced chronic kindling APP mice exhibited short-term spatial memory impairment, long-term learning and memory impairment and anxiety-like behaviour." (PMID 38388921, 2024). "On the basis of our results, we concluded that TSA intervention relieved anxiety- and depression-like behavior in APP/PS1 mice." (PMID 38572429, 2024). "We found that the HS diet increased anxiety and cognitive decline and aggregated the neuron loss in the hippocampal CA1 region in APP/PS1 mice." (PMID 39519278, 2024). "This APP mouse model showed hyperactivity in the open field test and lower anxiety in the elevated plus maze." (PMID 39443966, 2024). "Meanwhile, hippocampal SIRT1 signaling mediates the ameliorative effect of treadmill exercise on anxiety- and depression-like behavior in APP/PS1 mice." (PMID 39744519, 2024). "Taken together, these results suggest that hippocampal SIRT1 mediates the ameliorative effect of exercise on anxiety- and depression-like behaviors in APP/PS1 mice through the PGC-1α/NRF1/TFAM/mitochondrial biogenesis pathway." (PMID 39744519, 2024). "In total, hippocampal SIRT1 regulates the SIRT1/PGC-1α/NRF1/TFAM/mitochondria biogenesis axis to mediate the ameliorative effect of treadmill exercise on anxiety- and depression-like behaviors in APP/PS1 mice." (PMID 39744519, 2024). "Curiously, repetitive exposures reduced anxiety as well as improved cognition and social interactions in APP/PS1 Tg, returning many behavioral parameters in APP/PS1 Tg mice to the levels of non-transgenic, wild-type mice." (PMID 38256223, 2024). "In APP/PS1 mice, anxiety-like behavior is associated with high levels of soluble Aβ in the hippocampus." (PMID 39703925, 2024). "A trend was observed between female and male APP;E4F mice, wherein females displayed less anxiety-like behavior than males (p = 0.0986)." (PMID 39273325, 2024). "We found that APP/PS1 mice exhibited anxiety- and depression-like behaviors, and exercise alleviated these behaviors in APP/PS1 mice." (PMID 39744519, 2024). "It is worth noting that a study using APP-NLGF knock-in mice has found conflicting anxiety profiles as shown by the increased thigmotaxis in OFT (i.e., anxiogenic) but reduced closed-arm time in EPM (anxiolytic)." (PMID 39703925, 2024). "In our study, we tested SDS-induced anxiety using 6- to 7-month-old APP/PS1 mice that typically develop spatial cognitive impairment at 7–8 months of age." (PMID 37032820, 2023). "Chemogenetical activation of VTAVgat neurons improved sleep quality and further reduced anxiety in APP/PS1 mice." (PMID 37032820, 2023). "Capsaicin appears to increase anxiety-like behaviours, such as rearing, in APP/PS1 mice, but hippocampal damage can also impair rearing, possibly through impaired spatial memory and novelty detection." (PMID 37373321, 2023). "In conclusion, we found that acute SDS led to anxiety in APP/PS1 mice, and the activation of VTAVgat neurons by DCZ alleviated the anxiety." (PMID 37032820, 2023). "For example, in some studies, 5xFAD and APP/PS1 mice exhibited decreased or equivalent anxiety-like behavior in the open field or elevated plus maze relative to WT mice." (PMID 37513464, 2023). "Second, the AD pathology in the APP mice impairs neural networks important for controlling anxiety that are separate from those important for learning and memory functions centered on the HPC neural network." (PMID 37950055, 2023). "A notable observation is that Shank3 defects synergized with APP/tau transgenes to impair object recognition and precipitate anxiety-like behavior." (PMID 37253603, 2023). "In the present study, we found that SDS aroused anxiety and activated VTAVgat neurons in APP/PS1 mice, as previously reported." (PMID 37032820, 2023).
Anxiety (continued). "While in males, measures of anxiety in the open field revealed an APP × APOE interaction at the 6-month time point, measures of anxiety in the elevated zero maze revealed an APP × APOE interaction at the 18-month time point." (PMID 35299942, 2022). "The introduction of PPARα agonists reduces the accumulation of Aβ peptide, improves memory, and reduces anxiety in APP-PSEN1ΔE9 mice (AD model)." (PMID 35457077, 2022). "The APP KI mice did demonstrate decreased anxiety as demonstrated by the EPM, as previously shown, which was not changed by 14-3-3θ overexpression." (PMID 35697511, 2022). "First, we evaluated different behavioral domains including anxiety, cognitive functions, and social interactions in male and female APP/PS1 mice at 4 months of age." (PMID 35370697, 2022). "Both APP/PS1 and APP/PS1/eNOS+/− groups spent significantly more time in the outer zone of the apparatus relative to the WT group, indicative of a higher level of anxiety in mice with APP and PS1 mutations." (PMID 35806318, 2022). "The behavioural experiments indicate that APP/PSEN1-Tg mice showed early anxiety-like and depressive-like traits, symptoms which would be expected to be associated with dysfunction of the amygdaloid, hippocampal and PFC circuitries." (PMID 33795014, 2021). "In the same line, IHC was also shown to improve cognitive performance and reduce anxiety-related behavior in APP/PS1 mice." (PMID 33466445, 2021). "Taken together, these results demonstrated that forebrain neuron-specific deletion of FT reduced anxiety and improved spatial learning and memory function in APP/PS1 mice." (PMID 34315531, 2021). "In the open-field test, APP/PS1 mice showed less anxiety and better exploratory after treatment of tan IIA (5 and 20 mg/kg)." (PMID 33054814, 2020). "It is the first to investigate the effects of IH exposure on spatial memory, cognition, and anxiety‐related behavior in the APP/PS1 mouse model of AD." (PMID 31877583, 2020). "We also observed slightly mitigated anxiety-like behavior of APP/PS1 mice treated with CPPs, further studies are required to analyze the pharmacological function of CPPs on anxiety." (PMID 32652518, 2020). "Our results indicated that exposure to IH improves memory functions and suppresses anxiety‐related behaviors in APP/PS1 mice." (PMID 31877583, 2020). "These authors also found similar time-dependent changes in anxiety behavior in APP mice (which bear amyloid-β pathology), but at even earlier ages (however, it does not appear that c-Fos was examined in the PPT in these APP mice)." (PMID 33013301, 2020). "The present study is the first to investigate the effects of IH exposure on spatial memory, cognition, and anxiety‐related behavior in the APP/PS1 mouse model of AD." (PMID 31877583, 2020). "Stimulating pBLA–vCA1 inputs not only ameliorated anxiety but also improved spatial memory in APP/PS1 mice." (PMID 31924799, 2020). "Compared with the WT group, APP/PS1 mice showed anxiety and less movement in exploring the central zone as indicated by less time spent in the center, fewer numbers of central entries, and shorter distance in the center." (PMID 33054814, 2020). "In summary, CSP did not influence locomotor activity and only partially reversed anxiety-related behavioral in APP mice." (PMID 29535835, 2018). "Increased anxiety, impaired cognitive capability, and glucose utilization in APP/PS1 mice were also found in other studies." (PMID 28398234, 2017). "In these two tests, the APP/DcR3 mice also had higher locomotor activity and lower anxiety-like behavior similar to the APP mice." (PMID 28438208, 2017). "In the open‐field test, the vehicle‐treated APP/PS1 mice showed increased anxiety, as evidenced by less time spent in the center of the open field compared with the vehicle‐treated wild‐type controls." (PMID 27457264, 2016).
Anxiety (continued). "There are also reports indicating that APP/PS1 mice exhibit decreased levels of anxiety, as assessed by EPM, while others fail to replicate the anxiety-like phenotype." (PMID 27814403, 2016). "The results of the EZM show that APP/PS1 mice have elevated anxiety levels, since they spent less time in the open arms of the maze." (PMID 26379542, 2015). "We previously reported that the APP SL knock-in mice exhibit anxiety phenotypes starting at young age." (PMID 25108425, 2014). "The anxiety-related behavior of APP/PS1 KI and WT mice was assessed by two behavioral tests: analysis of time spent in the center zone versus peripheral zone of the open field arena; and the elevated plus maze task." (PMID 23705774, 2013). "We previously reported an increased anxiety-related phenotype of the APP and APP/PS1 mouse models due to central corticotrophin-releasing factor system perturbation." (PMID 24278307, 2013). "Open field testing also provided a coarse measure of anxiety, another common phenotype in APP transgenic mice." (PMID 22709352, 2012). "The higher depression behavior in APP/IR‐dKI mice may be induced by insulin resistance, especially in the brain, and the lower anxiety behavior may be elicited by peripheral insulin resistance." (PMID 40443027, 2025). "Notably, at 7.5 months, female APP/Ps1 mice spend significantly more time in the center of the arena, reflecting either reduced anxiety-like behavior or altered exploratory behavior at a younger age." (PMID 41300242, 2025). "The reduced time in the open field center in APP/PS1/Hif-p4h-2wt/wt mice by age may result from a reduced exploratory drive upon repeated exposure to the same environment or increased level of anxiety for an open place with age." (PMID 40609789, 2025). "Ginsenoside Ro significantly improved cognitive function and reduced anxiety in APP/PS1 mice." (PMID 40066331, 2025). "Anxiety of APP/IR‐dKI mice was examined in the light/dark box test." (PMID 40443027, 2025). "Anxiety‐like behavior in APP/PS1 mice was also evaluated using the elevated plus maze (EPM) test." (PMID 38606360, 2024). "To assess whether APP/PS1 mice show age‐dependent anxiety‐like behavior, we first employed the open‐field test and recorded the percentage of time spent in the central area of the test apparatus." (PMID 38606360, 2024). "However, a trend towards decreased anxiety-like behavior was noted in both APP-positive and SEM-treated groups, suggesting a potential anxiolytic effect of SEM, albeit not statistically significant." (PMID 39767596, 2024). "We hypothesized that acute social defeat stress (SDS) would lead to anxiety in APP/PS1 mice, and that the activation of VTAVgat neurons would alleviate this anxiety." (PMID 37032820, 2023). "Notably, APP/PS1 transgene-associated hyperactivity, often engaging as anxiety-like behavior, was fully reversed by 6KApoEp treatment (†p < 0.05 for each 6KApoEp- versus each vehicle-treated APP/PS1/E2/E3/E4 mice)." (PMID 37211092, 2023). "Additionally, the deficiency in human APP/PS1 transgenic mice can be alleviated with overexpression of EPHB2 with improved impaired memory, depression, and anxiety-like behaviours." (PMID 37186582, 2023). "Activation of these neurons also has anxiety-reducing effects in APP/PS1 mice." (PMID 37032820, 2023). "It is noteworthy that the administration of Verapamil resulted in a reduction in anxiety levels in mice with APP, as evidenced by an increase in the amount of time spent exploring the central area of the arena compared to the baseline (105.762 ± 12.638 s, p = 0.0008." (PMID 37833922, 2023). "However, we found that APP/PS1 mice displayed higher anxiety-like behavior when compared to the WT mice, as the latter spent more time in the center of the open field (WT: 27.91 ± 6.20%, APP/PS1: 4.85 ± 1.44%, p = 0.0003, n = 5–11)." (PMID 37108131, 2023).
Anxiety (continued). "Additionally, APP/PS1 group presented an obvious anxiety-like behavior with shorter central region distance, while Tan IIA relieved the symptom in the open field test." (PMID 36670462, 2023). "In this study, we investigated whether the activation of VTAVgat neurons could reduce anxiety in APP/PS1 mice." (PMID 37032820, 2023). "Our study provides evidence that the activation of VTAVgat neurons alleviates SDS-induced anxiety in APP/PS1 mice, suggesting that poor sleep quality may exacerbate anxiety in AD." (PMID 37032820, 2023). "We found that, as expected, SDS induced anxiety in APP/PS1 mice." (PMID 37032820, 2023). "Therefore, we examined cognitive function and anxiety-like behavior of APP/PS1 mice at 4 months old by the Y-maze and EPM testing, respectively." (PMID 36186142, 2022). "When taking all behavioral data together, the present study demonstrated that partial eNOS deficiency aggravated the spatial working memory deficit in APP/PS mice, but did not affect locomotion, exploration, anxiety, and spontaneous alternation behavior." (PMID 35806318, 2022). "The higher incidence of anxiety and depression with less irritability is also well represented in PSEN1 and PSEN2, but they tend to have more hallucinations and delusions compared with APP mutations." (PMID 36313020, 2022). "Interestingly, in the elevated plus maze test, APP/PS1/FTnKO mice spent significantly longer time in the open arm than APP/PS1 mice on the second day of the test, suggesting that forebrain neuronal FT deletion reduced anxiety in APP/PS1 mice." (PMID 34315531, 2021). "The hyperactivity exhibited by our APP mice may underpin similar vagaries in decision‐making, and contribute to the apparent working memory deficit and anxiety‐like behavior in these mice." (PMID 32557778, 2020). "Previous studies have reported that APP/PS1 mice also exhibit anxiety‐related behaviors." (PMID 31877583, 2020). "Interestingly, anxiety status was significantly correlated with spatial memory deficits in 6–8 months APP/PS1 mice." (PMID 31924799, 2020). "IFY could reduce anxiety and improve memory and spatial cognition in APP/PS1 mice according to the behavioral tests." (PMID 32784451, 2020). "To examine whether the increased distance traveled by APP/PS1+Tau mice resulted from anxiety, we examined the distance traveled in the inner versus the outer portions of the arena." (PMID 31825838, 2019). "It is speculated that this stereotyped behavior reflecting the increased anxiety of APP/PS1 mice, and which might be used as an important behavioral indicator in analysis of transgenic mouse models of AD." (PMID 29463001, 2018). "However, insulin treatment significantly alleviated anxiety in the APP/PS1 mice to a level comparable to wild‐type controls, as indicated by the increased percent of time spent in the center compared with APP/PS1‐veh mice." (PMID 27457264, 2016). "These alterations in the APP/PS1 mice could be explained by changes in anxiety-related and general locomotor behavior, specific of AD." (PMID 26379542, 2015). "This could be due to several factors; e.g., increased anxiety suppressing the APP/PS1 mice to void, decreased fluid intake due to behavioral impairment resulted in reduce urine production." (PMID 26379542, 2015). "In addition, isolated APP/PS1 mice exhibited mild anxiety-like behaviors, reflected by a tendency to increase movement speed (P=.484) and defecation number (P=.203)." (PMID 25568286, 2015). "Here we seek to fill this void in knowledge by examining the cognition/behavioral profile (motor behavior, anxiety-related behavior, and cognitive function) across the lifespan of the APP/PS1 KI mouse using a cross-sectional design (age groups of 7, 11, 15, and 24 months old)." (PMID 23705774, 2013). "In the present study, we also found similar levels of increased anxiety in APP/PS1/htau mice." (PMID 24278307, 2013).